BTG2 (BTG anti-proliferation factor 2)
Diseases named in the same sentence as BTG2 in open-access papers (continued):
Sharing a sentence is not in itself a finding about the gene and the disease.
pancreatic cancer (continued). "To explore the downstream regulatory target gene of miR-361-3p, we adopted TargetScan prediction and found that miR-361-3p had a binding site with BTG2 in the pancreatic cancer cells." (PMID 33425718, 2020). "To conclude, circRNA_000864 and BTG2 exercise their antioncogenic effects on pancreatic cancer, while miR-361-3p exercises its oncogenic effects on pancreatic cancer." (PMID 33425718, 2020). "CircRNA_000864, miR-361-3p, and BTG2 expression patterns in the pancreatic cancer tissues were detected by RT-qPCR." (PMID 33425718, 2020). "The current study aims to determine the interaction between circRNA_000864, miR-361-3p, and BTG2 in pancreatic cancer, and their effects on pancreatic cancer cell proliferation, invasion, and apoptosis." (PMID 33425718, 2020). "Several studies have reported that BTG2 expression is downregulated in some cancers, including laryngeal carcinoma, pancreatic cancer and renal cell carcinoma." (PMID 29656435, 2018). "We found that BA could reduce the expression of IL-6 and the ratio of p-STAT3/STAT3 and p-AKT/AKT by mediating miR-365/BTG2, which may be one of the mechanisms of BA in anti-pancreatic cancer." (PMID 37415745, 2023). "Finally, the expression of miR-21-5p was elevated in pancreatic cancer tissue samples, while BTG2 was reduced." (PMID 36789695, 2022). "Finally, miR-21-5p expression is increased, while BTG2 expression is decreased in pancreatic cancer tissues." (PMID 36789695, 2022). "Since BTG2 has been reported to be targeted by several miRNAs within pancreatic carcinomas, such as miR-21 and miR-27a, we speculate that there might be other miRNAs mediating the crosstalk between DSCR9 and BTG2 in pancreatic cancer cells." (PMID 36789695, 2022). "Btg2 was expressed at low levels in pancreatic cancer tissue compared with adjacent normal tissues." (PMID 35045793, 2022). "Thus, the DSCR9/miR-21-5p axis regulates the proliferation, invasion, and gemcitabine resistance of pancreatic carcinoma cells via BTG2." (PMID 36789695, 2022). "Moreover, miR-27a is determined to enhance angiogenesis in pancreatic cancer by targeting at BTG2, which is concordant with our finding in CRC." (PMID 34699325, 2021). "Besides, it is further documented that BTG2 participates in the regulation of angiogenesis in miR-27a-mediated development of pancreatic cancer." (PMID 34699325, 2021). "Additionally, studies have demonstrated that cyclic circRNA_000864 absorbs miR-361, relieves the inhibitory effects on the target gene BTG2 in the pancreatic cancer, and promoted tumor proliferation and tumorigenesis." (PMID 34348712, 2021). "Upregulating circRNA_000864 expression could upregulate impaired BTG2 and inhibit the proliferation, invasion, migration, and antiapoptosis of pancreatic cancer cells by binding to miR-361-3p." (PMID 33425718, 2020). "In order to study the effect of circRNA_000864 regulating BTG2 on the biological function of the pancreatic cancer cells, we initially interfered with the BTG2 expression and then tested the proliferation, migration and invasion ability, cell cycle progression, and apoptosis." (PMID 33425718, 2020). "Moreover, in the current study, BTG2 decreased the proliferation, migration and invasion, cell cycle entry, and induced the apoptosis of pancreatic cancer cells." (PMID 33425718, 2020). "The results exhibited that BTG2 was lowly expressed in pancreatic cancer tissues." (PMID 33425718, 2020). "Since miR-361 was highly expressed in pancreatic cancer, and miRNAs usually inhibit the expression of target genes, we speculated that miR-361-3p may target BTG2 in pancreatic cancer." (PMID 33425718, 2020). "Hence, the aim of this study is to elucidate the mechanism of circRNA_000864 in regulating BTG2 expression in pancreatic cancer by binding to miR-361-3p." (PMID 33425718, 2020). "Our findings indicated that circRNA_000864, miR-361-3p, and BTG2 could function as potential targets for the treatment of pancreatic cancer." (PMID 33425718, 2020).
pancreatic cancer (continued). "BTG2 was poorly expressed in pancreatic cancer, while ARL4C was highly expressed." (PMID 33425718, 2020). "Thus,BTG2 functions as an antiproliferative gene in tumorigenesis and the effect of DSCR9 in pancreatic cancer cells might be related to BTG2." (PMID 36789695, 2022). "Conjointly, our findings elicited that the overexpression of circRNA_000864 could promote BTG2 expression to inhibit pancreatic cancer development by binding to miR-361-3p, which represents an appealing therapeutic target for the treatment of pancreatic cancer." (PMID 33425718, 2020). "Therefore, circRNA_000864 was speculated to mediate BTG2 via miR-361-3p to influence pancreatic cancer development." (PMID 33425718, 2020). "For example, in pancreatic cancer, exosomal miR-30b-5p promotes tumor angiogenesis by inhibiting GJA1, while miR-27a promotes angiogenesis by targeting BTG2." (PMID 39596828, 2024). "BA inhibits the proliferation, migration, and invasion of pancreatic cancer cells in vivo and in vitro through inhibiting IL-6 protein expression and AKT/STAT3 protein phosphorylation by mediating miR-365/BTG2 axis." (PMID 37415745, 2023). "To validate the specific roles of BTG2 in pancreatic carcinoma cells, we infected PANC-1 and MIAPaCa-2 cells with lv-BTG2 to generate BTG2-overexpressing cells and performed real-time PCR to verify the infection efficiency." (PMID 36789695, 2022). "After confirming the binding of miR-21-5p to DSCR9 and the BTG2 3′UTR, the specific roles of miR-21-5p in the pancreatic carcinoma phenotype were validated." (PMID 36789695, 2022). "After confirming which clones did not express miR-21, we measured the basal expression of PDCD4 and BTG2 in three PANC-1 KO miR-21 clones (c4, c5 and c6), and compared it with the control pancreatic cancer cell line PANC-1 expressing high levels of miR-21." (PMID 29464088, 2018). "In order to experimentally evaluate some of these miR-21 predicted targets in the context of pancreatic cancer, we selected PDCD4 and BTG2 from that list for being also highly down-regulated in PDAC (FC=-7.88 and FC=-5.53, respectively)." (PMID 29464088, 2018). "We discovered that the overexpression of BTG2 could suppress cell migration, colony formation, and EMT response in Panc02 and SNU2491 pancreatic cancer cells." (PMID 36765032, 2023). "As shown inFigure 7A,B, the expression of miR-21-5p was dramatically increased, whereas the expression of BTG2 was decreased in pancreatic cancer tissue samples compared with those in noncancerous tissues." (PMID 36789695, 2022). "As a further confirmation, we examined miR-21-5p and BTG2 expression in 15 paired pancreatic cancer and noncancerous tissue samples." (PMID 36789695, 2022). "Moreover, FISH and IF staining results showed that both BTG2 (green fluorescence) and DSCR9 (red fluorescence) levels were upregulated in adjacent tissues compared to those in pancreatic cancer tissues." (PMID 36789695, 2022). "Since miR-21-5p directly targets DSCR9 and the BTG2 3′UTR, the dynamic effects of DSCR9 and miR-21-5p on BTG2 expression and pancreatic cancer cell phenotype were examined to determine whether DSCR9 and miR-21-5p exert their functions via BTG2." (PMID 36789695, 2022). "More importantly, the tumor-suppressive effects of DSCR9 overexpression on pancreatic cancer cells were significantly reversed by miR-21-5p overexpression, whereas the suppressive effects of DSCR9 overexpression on BTG2 expression were reversed by miR-21-5p overexpression." (PMID 36789695, 2022). "As a further confirmation of thesein vitro findings, miR-21-5p expression was significantly increased, while BTG2 expression was decreased in pancreatic carcinoma tissues compared with those in noncancerous tissues." (PMID 36789695, 2022).
pancreatic cancer (continued). "Moreover, we detected ARL4C and BTG2 expression in pancreatic cancer tumor tissues and adjacent normal tissues and found that BTG2 was downregulated and ARL4C was upregulated in pancreatic cancer tumor tissues compared with adjacent normal tissues." (PMID 33425718, 2020). "In order to experimentally evaluate if some of these predicted targets could act as miR-21 targets in the context of pancreatic cancer, we selected 2 targets (PDCD4, BTG2) from the top miR-21 targets list." (PMID 29464088, 2018). "However, adequately powered clinical trials testing the effect of circRNA_000864/miR-361-3p/BTG2 axis on pancreatic cancer treatment are lacking." (PMID 33425718, 2020).
glioma (17 papers, 2010 to 2026). A benign or malignant brain and spinal cord tumor that arises from glial cells (astrocytes, oligodendrocytes, ependymal cells). "We therefore tested whether the downregulation of Btg2 is sufficient and necessary for glioma progression with loss and gain of function experiments." (PMID 23203087, 2012). "Circ-ZNF609 positively regulated the expression of BTG-2 through competitively binding to miR-134-5p, leading to the proliferation and migration of glioma." (PMID 35938040, 2022). "Another study reported that circZNF609 regulates glioma cell migration and proliferation via the miR-134-5p/BTG-2 axis." (PMID 35236250, 2022). "For example, circZNF609 sponges miR-134-5p to promote BTG-2 expression as a ceRNA, thus weakening proliferation and migration of glioma cells." (PMID 33413401, 2021). "Accordingly with this view, the analysis of public datasets of human gliomas showed that reduced level of Btg2 expression correlates with a significantly worse prognosis." (PMID 23203087, 2012). "Gliomas cells secret vesicles containing miR-21, which are taken up by microglia to downregulate mRNA targets and increase proliferation after the downregulation of Btg2 (a tumour suppressor), shaping an immune microenvironment favourable for gliomas progression." (PMID 38212785, 2024). "Besides, exosomal circ-BTG2 or circ_0004658 secreted from RBP-J overexpressed-macrophages inhibited glioma or HCC progression by regulating miR-25-3p/PTEN or miR-499b-5p/JAM3 pathway, respectively." (PMID 37525158, 2023). "Moreover, RBP-J-overexpressed- macrophage-derived exosomal circ-BTG2 or circ_0004658 inhibit glioma or HCC progression." (PMID 37525158, 2023). "Interestingly, the role of Btg2 is not limited to murine PDGF-induced oligodendroglioma model but rather it seems to be extended also to human gliomas." (PMID 23203087, 2012). "In particular it will be interesting to ascertain whether Btg2 overexpression is correlated to a decrease of glioma initiating cells, or to a switch in mode of cell division, from symmetric to asymmetric, reminiscent of that induced by Btg2 during neurogenesis." (PMID 23203087, 2012). "Furthermore, in glioma, PC3/Tis21/BTG2 enhances apoptosis rates while simultaneously decreasing the migration and invasion of cancerous cells, and lowering the levels of cyclin D1." (PMID 42080092, 2026). "In addition, circZNF609/miR-134-5p/BTG-2 axis and circ_0076248/miR-181a/SIRT1 axis have also been disclosed in glioma." (PMID 34057019, 2021). "Here we show that the putative tumor suppressor gene Btg2 is consistently downregulated in high grade gliomas and that its downregulation, although not sufficient to allow the tumor progression, is necessary for a cell to maintain the malignant phenotype." (PMID 23203087, 2012).
hepatocellular carcinoma (16 papers, 2013 to 2024). A malignant tumor that arises from hepatocytes. "CirRNA_0014717 suppresses the progression of hepatocellular cancer by modulating the miR-668-3p/BTG2 signaling pathway." (PMID 38454507, 2024). "PRMT5 inhibits the expression of BTG2 in hepatocellular carcinoma through the ERK signaling pathway, thereby promoting cell proliferation." (PMID 34476262, 2021). "BTG2 is down-regulated in hepatocellular carcinoma and its low expression is related to poor clinicopathological features, and participates in the inhibition of cancer stem cell-like features of side population cells." (PMID 34082648, 2021). "A study showed that BTG2 expression is downregulated in hepatocellular carcinoma and that it suppressed stem cell-like characteristics adjacent to cancer." (PMID 34187411, 2021). "Xie et.al demonstrated that miR-6875-3p promotes the proliferation, invasion and metastasis of hepatocellular carcinoma by mediating BTG2/FAK/Akt pathway." (PMID 34861847, 2021). "BTG2 inhibited the hepatocellular carcinoma cell invasion and metastasis." (PMID 31959200, 2020). "The current body of evidence indicates that berberine can promote the cell cycle arrest of human hepatoma HEPG2 cells in the G1 phase through the upregulation of BTG2 and the downregulation of cyclin D1, consequently inhibiting the proliferation of hepatoma cells and inducing apoptosis." (PMID 30837865, 2019). "In hepatocellular carcinoma, PRMT5-catalyzed repressive dimethylation on H4R3 at the B-cell translocation gene 2 (BTG2) promoter increases cell proliferation through the ERK signaling pathway." (PMID 34685445, 2021). "BTG2, a tumor suppressor in various malignancies, is absent or down-regulated in multiple tumors, for instance, gastric carcinoma, hepatocellular carcinoma and non-small cell lung carcinoma." (PMID 34082648, 2021).
triple-negative breast carcinoma (11 papers, 2016 to 2024). An invasive breast carcinoma which is negative for expression of estrogen receptor (ER), progesterone receptor (PR), and human epidermal growth factor receptor 2 (HER2). "Loss of BTG2 promotes tumor growth and reduces survival in patients with triple-negative breast cancer." (PMID 36765032, 2023). "Zhang also found that BTG2 can promote or induce apoptosis of triple negative breast cancer cells and inhibit cell invasion." (PMID 37006240, 2023). "Among genes with a high score predicting targeting by miR-25-3p, B-cell translocation gene 2 (BTG2) is related to triple negative breast cancer, and miR-25-3p promotes the proliferation of breast cancer." (PMID 32968200, 2020). "BTG2 is considered as a tumor suppressor gene in a variety of tumors, and it has been reported that BTG2 inhibits proliferation, invasion, and induces apoptosis of triple-negative breast cancer cells." (PMID 29310680, 2018). "Our prediction analyses showed that BTG2 is a putative target of miR-25-3p, so it seems possible that this miRNA may promote proliferation by targeting BTG2 in triple negative breast cancer." (PMID 31485228, 2019). "A decrease in BTG2 level could indirectly activate AKT and extracellular signal-regulated kinase/mitogen-activated protein kinase signaling pathways and regulate the downstream effects of miR-25-3p to stimulate proliferation of triple-negative breast cancer cells." (PMID 31223310, 2019).
bladder cancer (10 papers, 2018 to 2025). "The BTG2 expression is downregulated in many human cancers acting as a tumor suppressor, including bladder cancer." (PMID 34861847, 2021). "But it still needs more experiments to investigate the concrete signaling pathway and mechanisms between miR-93-5p and BTG2 in bladder cancer." (PMID 34861847, 2021). "Meanwhile, a lower expression of BTG2 was evident in bladder cancer tissues compared to the normal bladder tissues." (PMID 33425718, 2020). "Further measurement from paired normal and cancerous bladder tissues revealed that bladder cancer tissues presented with lower BTG2 mRNA expression (∆∆CT = 1.85) in comparison with bladder normal tissues." (PMID 29239139, 2018). "Our results suggested that modulation of BTG2 expression is a new therapeutic direction for human bladder cancer." (PMID 29239139, 2018). "In this study, we demonstrated that BTG2 served as a tumor suppressor gene in human bladder cancer in vitro and in vivo and lower BTG2 expression was found in human bladder cancer tissues as compared to normal bladder tissues." (PMID 29239139, 2018). "Our results suggest that modulation of BTG2 expression is a promising direction for bladder cancer treatment." (PMID 29239139, 2018). "Our results indicate that human bladder cancer exhibited lower BTG2 mRNA and protein expression as compared to normal bladder tissues." (PMID 29239139, 2018). "To evaluate BTG2 role in human bladder cancer, we stably transfected BTG2 into T24 cells, and obtained T24‐BTG2‐1 and T24‐BTG2‐2 cells." (PMID 29239139, 2018). "In this study, we investigated the roles of BTG2 and PTEN as well as the regulatory mechanisms of BTG2 in human bladder cancer." (PMID 29239139, 2018). "Although widely deemed as a tumor suppressor gene, the role of B‐cell translocation gene 2 (BTG2) in bladder cancer is still inconclusive." (PMID 29239139, 2018). "Collectivley, our results indicated that BTG2 expression in human bladder cancer cells was stimulated by PTEN." (PMID 29239139, 2018). "On the contrary, one report indicated that endogenous expression of BTG2 stimulated the migration of bladder cancer cell and higher BTG2 expression correlated with poor survival of patients with bladder cancer." (PMID 29239139, 2018). "Collectively, our results indicated that PTEN repressed cell growth of the bladder cancer in vitro, and negatively modulated BTG2 mRNA expression in bladder cancer cell." (PMID 29239139, 2018). "What’s more, exosomal miR-93-5p suppressed BTG2 expression and promoted bladder cancer cells progression, exosomal EphA2 promoted the invasion and migration of bladder cancer cells, exosomal CDC6 effectively repressed the malignant process of bladder cancer cells." (PMID 37805491, 2023). "In this study, we reveal that BTG2 act as s tumor suppressor in bladder cancer and overexpression of miR-93-5p inhibited BTG2 and then promote the proliferation, migration and invasion of bladder cancer cell." (PMID 34861847, 2021). "We investigated the role and regulatory mechanism of BTG2 in bladder cancer." (PMID 29239139, 2018). "Thus, we concluded that PTEN insufficiency would increase cell growth of the human bladder cancer with BTG2 positively regulated by PTEN." (PMID 29239139, 2018). "Modulation of BTG2 expression seems a promising way to treat human bladder cancer." (PMID 29239139, 2018).